GOLGA8J (golgin A8 family member J)
Tractability: PROTAC: ubiquitination databases record sites on it.
Gene: Protein-coding gene on chromosome 15 (30,082,955 to 30,096,690, forward strand). Ensembl gene ENSG00000179938.
Gene Ontology:
Biological process: Golgi organization
Cellular component: cis-Golgi network; Golgi cis cisterna; Golgi cisterna membrane; Golgi apparatus
Genetic constraint (gnomAD): Loss-of-function variants: 11 observed, 22.11 expected, observed/expected ratio (o/e) 0.5, 90% interval 0.31 to 0.82. The synonymous counts are far from expectation, so gnomAD's model fits this gene poorly and the ratio says little. Missense variants: 135 observed, 198.88 expected, observed/expected ratio (o/e) 0.68, 90% interval 0.59 to 0.78. Synonymous variants: 48 observed, 73.85 expected, observed/expected ratio (o/e) 0.65, 90% interval 0.51 to 0.83.
Homologues: Orthologues: mouse Golga2 (44% identical), dog GOLGA2 (43% identical), tropical clawed frog golga2 (34% identical), zebrafish golga2 (29% identical), Drosophila melanogaster GM130 (22% identical), Caenorhabditis elegans golg-2 (19% identical), rat Golga2l1 (5% identical). Paralogues in human: GOLGA8H (98% identical), GOLGA8T (97% identical), GOLGA8K (97% identical), GOLGA8M (97% identical), GOLGA8O (91% identical), GOLGA8N (90% identical), GOLGA8Q (90% identical), GOLGA8R (90% identical), GOLGA8S (85% identical), GOLGA8F (81% identical), GOLGA8G (81% identical), GOLGA8A (66% identical), and 6 more.